USP32 (ubiquitin specific peptidase 32)
Diseases named in the same sentence as USP32 in open-access papers (continued):
Sharing a sentence is not in itself a finding about the gene and the disease.
tumor (continued). "USP32 overexpression could significantly increase CRC tumour weight and volume, while the knockdown of USP32 had opposite functions." (PMID 40122703, 2025). "We found that USP32 downregulation could suppress CRC tumour growth while overexpressing USP32 in CRC cells had the opposite function." (PMID 40122703, 2025). "In vitro experiments confirm that USP32 promotes tumor growth." (PMID 37679322, 2023). "In this study, USP32 knockdown inhibited cell growth and metastasis in vitro, and suppressed tumor growth in vivo, which suggests that USP32 acts as an oncogene in GBM and may serve as a potential target for GBM treatment." (PMID 35440702, 2022). "In addition, IHC analysis of DLD1 and HCT116 xenograft tumours confirmed that USP32 could positively regulate the NF‐κB signalling pathway." (PMID 40122703, 2025). "Thus, USP32-specific inhibitors are promising therapeutic drugs for tumor therapies." (PMID 40136417, 2025). "Therefore, USP32 is a key and promising therapeutic target for tumor therapy, which could provide important new insights and avenues for antitumor drug development." (PMID 37679322, 2023). "These suggest that USP32 may contribute to tumor immune escape in HCC." (PMID 37957631, 2023). "Consistent with the in vitro results, LBT administration significantly decreased the protein expression levels of USP32 and NRF2 in tumor tissues." (PMID 40136417, 2025). "To further verify the role of USP32 in CRC tumour immunity, we also explored the positive regulatory relationship between USP32 expression and the infiltration of MDSC and M2 macrophage cells in CRC tumours." (PMID 40122703, 2025). "Subsequently, we analyzed the relationship between USP32 and BAG3 using the percentage of positive tumor cells of USP32 and BAG3, and found that the expressions of USP32 and BAG3 in NSCLC tissues were significantly positively correlated." (PMID 39030175, 2024). "Our study showed that USP10, USP14, USP18, USP32, USP33, and USP39 (termed as six-USPs) expressions were significantly elevated in tumor tissues." (PMID 36582601, 2022). "USP32 expression was decreased in USP32KO groups and SLC35F2 expression was upregulated in these tumor tissues." (PMID 34815782, 2021). "To further confirm the correlation, we analyzed USP32 and SLC35F2 expression in different human tumor tissues." (PMID 34815782, 2021). "Altogether, the depletion of USP32 enhances YM155-mediated sensitivity by stabilizing SLC35F2 protein, which hampers tumor progression." (PMID 34815782, 2021). "Wet experiments also confirmed that USP32 is critical for the proliferation, survival, and migration of CRC cells and tumour growth, which may be due to the activation of the NF‐κB signalling pathway." (PMID 40122703, 2025). "As a result, we found that USP32 overexpression could markedly enhance the fractions of infiltrating MDSCs and M2 macrophages in CT26 tumours, indicating its role in repressing anti‐tumour immunity." (PMID 40122703, 2025). "The results illustrated that the protein expression level of USP32 was markedly upregulated in tumor tissues compared with normal samples (p-value < 0.0001)." (PMID 37957631, 2023). "Wet experiments confirmed that knockdown of USP32 could repress the proliferation, colony formation and migration of HCC cells in vitro and inhibit tumor growth in vivo." (PMID 37957631, 2023). "Although the expression levels of USP10, USP32, and USP33 were also significantly related to tumor differentiation to some extent, the result may be unreliable due to the small sample size." (PMID 36582601, 2022).
adenocarcinoma of the (1 paper, 2017). "The GPR137 gene has also been identified in two fusions: with PAFAH1B2 and USP32 in adenocarcinoma of the lung and of the breast, respectively." (PMID 28186972, 2017).
USP32 also shares sentences with these, for which no sentence is quoted: ovarian cancer (3 papers); bone neoplasm (1); diabetes (1); esophageal carcinoma (1); head and neck squamous cell carcinoma (1); infection (1); intellectual impairment (1); liver cancer (1); Lung Squamous Cell Carcinoma (1); pancreatic adenocarcinoma (1); stomach adenocarcinoma (1); thymoma (1); thyroid carcinoma (1).